TNF (tumor necrosis factor)
Diseases named in the same sentence as TNF in open-access papers (continued):
Sharing a sentence is not in itself a finding about the gene and the disease.
psoriasis (continued). "An association between psoriasis and chronic PDIS has been shown, and increased concentrations of proinflammatory cytokines such as TNF-α and IL-1β have been found in saliva from patients with psoriasis." (PMID 28748036, 2017). "TNF-α is the major pro-inflammatory cytokine in psoriasis; it acts to upregulate other inflammatory mediators and regulates immune responses by stimulating Th1 lymphocytes to release various inflammatory and immune mediators." (PMID 29152103, 2017). "Sericin microspheres loaded with naringenin have previously been developed in our group for the topical treatment of middle-stage psoriasis, highlighting that the microencapsulated drug was more effective in the down regulation of TNF-α than as a free drug." (PMID 28832540, 2017). "Already approved for the treatment of PsA, etanercept was the first TNF-α inhibitor FDA approved for treatment of psoriasis in 2004." (PMID 29104241, 2017). "Blockage of TNF-α, by anti-TNF-α humanized monoclonal antibodies (Mabs), such as Infliximab Etanercept and Adalimumab, which bind with high affinity to TNF-α, has been shown to successfully treat psoriasis." (PMID 27415000, 2016). "We present the case of a 26-year-old stonemason with accelerated silicosis in the setting of treatment for psoriasis with the tumour necrosis factor alpha (TNF-alpha) inhibitor adalimumab." (PMID 27516887, 2016). "In summary, our study suggests that a complex remodelling of the TNF-α/sTNFR system occurs in patients with psoriasis treated with anti-TNF-α drugs." (PMID 27936119, 2016). "In particular, relationships have been evidenced between body composition and the occurrence of psoriasis, the severity of the disease, or the response to treatment with anti-TNF-α agents." (PMID 27165166, 2016). "In the current study, we demonstrated that psoriasis-like inflammation requires moDCs, which produce the critical cytokines, TNF and IL-1β, and depend on CCR6 for their optimal accumulation in the skin." (PMID 27982014, 2016). "TNF-α promotes and maintains chronic inflammation conditions such as psoriasis through induction of several pro-inflammatory cytokines." (PMID 27415000, 2016). "In psoriasis, T-cells (both CD4+ and CD8+) are known to cause low production of Th2 cytokines (IFNγ, TNFα, and IL-2) and high production of Th1 cytokines (IL-4, IL-6 and IL-10), leading to polarization of the type 1 pathway." (PMID 26849645, 2016). "We investigated early events in skin from psoriasis patients after treatment with anti-TNF-α antibodies by use of bioinformatics tools." (PMID 28005985, 2016). "Taken together, various types of immune cells produce the psoriasis-driving cytokines TNF, IL-17A, and IL-22." (PMID 27158469, 2016). "MiR-146a is found to modulate tumor necrosis factor-α (TNF-α) signalling in skin by inhibiting the expression of key protein of this pathway and thus perceived to play a role in the pathogenesis of psoriasis." (PMID 27054112, 2016). "Muscle loss, linked to the increased expression of tumor necrosis factor (TNF)-α, is commonly reported in psoriasis." (PMID 27165166, 2016). "These immunotherapeutics are highly effective in the treatment of psoriasis of skin and joints since they neutralize the effects of TNF on multiple cell types." (PMID 27158469, 2016). "Although the pathogenesis of psoriasis is not fully understood, evidence suggests that many cytokines, including IL-6, IL-17A, IL17F, IL-22, IL-23 and TNF-α, are involved and interact as a network in the pathogenesis of psoriasis." (PMID 27581210, 2016). "Certolizumab is a PEGylated Fab’ fragment of a humanised TNF inhibitor monoclonal antibody, which has been proven beneficial in treating psoriasis and PsA." (PMID 26892034, 2016). "Conversely, use of anti-TNF-α Mabs can lead to serious adverse side effects, other malignant diseases autoimmune diseases and development of skin lesions or psoriasis." (PMID 27415000, 2016).
psoriasis (continued). "One report showed the decreased platelet and endothelial MPs with clinical improvement after 3-month anti-TNF-α agents in patients with psoriasis." (PMID 27144162, 2016). "Significant relationships have been evidenced between body composition and the occurrence of psoriasis, the severity of the disease, or the response to treatment with anti-TNF-α agents." (PMID 27455297, 2016). "A number of clinical trials and observational studies have shown that anti-TNF-α drugs are effective in the treatment of psoriasis, as they reduce inflammation in psoriatic lesions and reverse disease activity." (PMID 27936119, 2016). "Of note, all immune cells mentioned also produce TNF, a factor well established in psoriasis pathogenesis and treatment." (PMID 27158469, 2016). "CVD and psoriasis have similar histology and molecular immune pathological basis, based on Th1 cytokines (TNF alpha, IL - 2, IL - 10, IL - 12)." (PMID 27245937, 2016). "Various proinflammatory cytokines, including IL-18, IL-17, IL-12, and TNF-α, which are elevated in psoriatic lesional skin and have critical roles in the pathogenesis of psoriasis, have been identified and targeted for psoriasis treatment." (PMID 26901187, 2016). "In clinical trials, etanercept, a tumor necrosis factor-alpha (TNFα) inhibitor, has been shown to be effective in managing psoriasis including improvements in Psoriasis Area Severity Index (PASI) scores, Physician’s Global Assessment (PGA), and QoL." (PMID 27455955, 2016). "RNA-seq was performed on skin samples from 18 psoriasis patients (pre-treatment and post-treatment with the TNF-α inhibitor adalimumab) and 16 healthy controls, generating an average of 52.3 million 100-bp paired-end reads per sample." (PMID 27793094, 2016). "Infliximab is a chimeric monoclonal antibody against TNFα, with demonstrated efficacy for treating psoriasis." (PMID 26892034, 2016). "Immunofluorescence staining of skin lesions from cutaneous lupus erythematosus and psoriasis patients has confirmed that slan/M-DC8+ cells are TNFα-positive also in tissues." (PMID 26695549, 2016). "The inflammation-driving actions of TNF in psoriasis are already well known and antibodies against TNF are successful in the treatment of Th17-mediated psoriatic skin inflammation." (PMID 27158469, 2016). "Anti-TNF-α drugs provide remission in a great proportion of patients, reducing inflammation and decreasing the “Psoriasis Area and Severity Index” (PASI)." (PMID 27936119, 2016). "The initiation of adalimumab, a biologic TNF-alpha inhibitor, was strongly considered for gaining better control of the patient's psoriasis." (PMID 27840756, 2016). "Other researchers have shown that the upregulation of CCR9 was associated with a poor response to infliximab, which is an anti-tumor necrosis factor-α (TNF-α) antibody drug used in psoriasis patients." (PMID 26879872, 2016). "T helper (Th) cells producing interleukin (IL)-17, IL-22, and tumor necrosis factor (TNF) form the key T cell population driving psoriasis pathogenesis." (PMID 27158469, 2016). "Further, up to 10% of IBD patients receiving anti-TNF therapy developed a new autoimmune disease, including psoriasis and dermatitis-like skin reactions." (PMID 27601345, 2016). "In patients with psoriasis, clinical data from treatment studies with antibodies against TNFα and IL-17, suggest that Th1 and Th17 cells play a significant role in development and progression of psoriasis." (PMID 27401543, 2016). "Many cytokines (e.g. interferon-γ, TNF-α, IL-6, IL-8, IL-12, IL-17, IL-19 and IL-23) involved in the pathogenesis of psoriasis are also known to contribute to the cascade of metabolic syndrome such as hypertension, dyslipidemia and insulin resistance." (PMID 27531132, 2016).
psoriasis (continued). "Anti-tumour necrosis factor (anti-TNF)-α agents have been approved for therapeutic use across a range of inflammatory disorders including psoriasis, but the anti-inflammatory mechanisms of anti-TNF-α in lesional psoriatic skin are not fully understood." (PMID 28005985, 2016). "Although parts of the literature are conflicting, there is evidence that circulating levels of TNFα (in addition to IFNγ, IL-12) are elevated in psoriasis and correlate with disease severity." (PMID 26573299, 2016). "Dermal CD11c+ cells in psoriasis skin outnumber lymphocytes and coincide with areas of TNFα and iNOS production." (PMID 25301671, 2015). "Here, we present a case of pulmonary sarcoidosis that developed during anti-TNF-α treatment for psoriasis and showed spontaneous regression after discontinuation of anti-TNF treatment." (PMID 26425632, 2015). "Although anti-TNF agents are effective in treating skin and nail lesions of psoriasis, treatment with anti-TNF agents also can result in new manifestations of psoriasis for some patients." (PMID 25888248, 2015). "Tetracyclines suppress cytokines, such as tumor necrosis factor-alpha (TNF-α), interleukin- (IL-) 1β, and IL-6, involved in inflammatory disorders as seborrheic dermatitis, psoriasis, acne, and rosacea." (PMID 25977597, 2015). "TNF is one of the key proteins in the development of psoriasis and drugs that inhibit TNF have been very successful in the treatment of this disease." (PMID 26701909, 2015). "Neutralization of TNFα was shown to be highly effective in treating the other complex diseases such as psoriasis and Crohn’s disease, with a profound impact on depressive mood." (PMID 26477946, 2015). "Psoriasis is characterized by over-proliferation and/or disturbed differentiation of keratinocytes, as well as by enhanced expression of tumor necrosis factor-α (TNF-α), IL-17 and IL-22 within the psoriatic skin." (PMID 26474319, 2015). "TNFα mediated NF-κB activation plays a central role in the pathogenesis of psoriasis as illustrated by the responsiveness to anti-TNFα therapy." (PMID 26124703, 2015). "In particular, patients with psoriasis respond to treatment interfering with lymphocyte activation, the tumor necrosis factor (TNF) pathway, agents blocking interleukin (IL)-17 or the IL-12/23p40 subunit." (PMID 27747495, 2015). "TNF-α and IL-8, two pivotal inflammatory factors according to previous reports, are both involved in the pathogenesis of psoriasis, and have been proposed to be the crucial therapeutic targets for psoriatic patients." (PMID 25574190, 2015). "In the first phase II study of apremilast in psoriasis, treatment with 20 mg QD resulted in a decrease in epidermal thickness, dendritic cell and T-cell skin infiltration, and TNF-α production in whole blood ex vivo." (PMID 25973439, 2015). "Our data contrast with a recent study performed in patients with psoriasis treated with the TNFα-inhibitor etanercept." (PMID 25860297, 2015). "TNF inhibitors are effective in the treatment of psoriasis as well as in RA; however they can induce antinuclear antibodies and even lupus." (PMID 26339139, 2015). "TNF-α inhibitors are effective in the treatment of psoriasis; however they can induce antinuclear antibodies and even lupus." (PMID 26339139, 2015). "Cytokines activate inflammatory and proliferative cascades in psoriasis lesions, as evidenced by the effectiveness of treatments directed against TNF, IL-17A and IL-23." (PMID 25883770, 2015). "Both TNF antagonists and ustekinumab can substantially improve symptoms of depression and health-related quality of life in patients with psoriasis." (PMID 26633680, 2015). "From 2000 on, it is worth noting the introduction of anti-tumor necrosis factor (anti-TNF) alpha therapies, which block the biologic activity of psoriasis." (PMID 26658481, 2015).
psoriasis (continued). "SNPs in the TNFAIP3 gene, but also in other immune-regulatory genes including HLA-C, TNIP1/ABIN-1 and IL-23A have been associated to psoriasis and polymorphisms in the TNFAIP3 gene correlate to responsiveness to TNFα blockers in psoriasis patients." (PMID 26124703, 2015). "It is believed that the inflammatory response in psoriasis leads to a Th1 lymphocyte cytokine milieu with increased levels of IL-1, IL-6, IL-8, TNF-α, and markers of systemic inflammation." (PMID 26700640, 2015). "In psoriasis patients treated with TNF-α blockers, a recent systemic review as well our study also suggested that presence of ADAs to infliximab and adalimumab is associated with loss of treatment response." (PMID 26566272, 2015). "The fact can be explained by differences in the usage of biological therapies, as all patients from the RA + psoriasis group were on TNF-alpha inhibitors, while in the control group only 1 patient received biological therapy." (PMID 26339139, 2015). "Approximately 60% of the top 20 upregulated genes, such as S100A12, SPRR2C, and CXCL1, have additive or synergistic responses to IL-17 and TNF, suggesting that these cytokines will be important for the creation of a molecular profile for psoriasis." (PMID 26362816, 2015). "Meanwhile TNF-α-antagonists have been developed and approved for treating a variety of inflammatory diseases including psoriasis." (PMID 26690116, 2015). "In recent years, biological therapies including anti-tumor necrosis factor (TNF)-α treatment have greatly increased therapeutic choices for patients with severe psoriasis." (PMID 26174087, 2015). "In this study, we show that curcumin at low concentrations (1.25–3.12 μM) has a strong anti-proliferative effect on TNF-α-induced psoriasis-like inflammation when applied in combination with light-emitting-diode devices." (PMID 26382065, 2015). "A randomized control trial using the TNF-α inhibitor, etanercept, revealed that treatment of inflammation in the setting of psoriasis results in measured improvements in fatigue and depressive symptoms." (PMID 26550011, 2015). "Efalizumab, an anti-monoclonal antibody which blocks T-cell functionality and infliximab a chimeric monoclonal antibody targeting TNF-α were also thought to result in thrombosis when used in psoriasis." (PMID 25884940, 2015). "Of interest, successful anti-inflammatory therapy of psoriasis patients with TNF-α antibodies led to suppression of GPX activity, while in nonresponders to the therapy, GPX activity was further stimulated." (PMID 26090072, 2015). "The exacerbation of psoriasis induced by anti-TNF therapy has also been described in a patient with AS after switching to treatment with ustekinumab." (PMID 26339141, 2015). "In contrast, genes induced by IL-17A (or IL-17A plus TNF) in cultured KCs tend to be more psoriasis-specific and less commonly elevated in other skin conditions." (PMID 26251673, 2015). "Weight changes are induced mainly by fat mass gain in patients with psoriasis receiving TNF-α antagonists." (PMID 25654080, 2015). "Another example of the tight relationship between psoriasis and IR is displayed by TNF-α, one of the major actors of psoriasis pathogenesis as demonstrated by the efficacy of anti-TNF-α treatments in psoriasis." (PMID 25977937, 2015). "Patients with psoriasis receiving TNF antagonists or methotrexate have lower cardiovascular event rates than patients treated with other medications." (PMID 26633680, 2015). "Tumour necrosis factor (TNF)-α is a critical pro-inflammatory cytokine in psoriasis immunopathology, over-expression of TNF-α is vital in pathogenesis of psoriasis, and suppression of TNF-α pathway is a key step in the regulation of psoriasis." (PMID 26382065, 2015). "Obesity can induce an overproduction of multiple proinflammatory cytokines in adipose tissue, including TNFα, IL-6 and IL-8, all of which are implemented in the pathogenesis of psoriasis." (PMID 27747495, 2015).
psoriasis (continued). "Interleukin-17 (IL-17) and tumor necrosis factor (TNF) are key proinflammatory cytokines in psoriasis, and we have recently shown that the RNA-seq based psoriatic skin transcriptome manifests a significant IL-17 stimulation signature." (PMID 25723451, 2015). "Comparison between patients with type I psoriasis and patients with type II psoriasis revealed significant associations for the following genes: FCGR2A, TNFR1, CD226, PSORS6, TNFAIP3, HLA-C, TNF-α, and CCHCR1." (PMID 26613086, 2015). "Some studies indicated that ghrelin has potent inhibitory effects on the mRNA and protein expression levels of proinflammatory cytokines, such as IL-6 and TNF-α, which are important in the pathogenesis of psoriasis." (PMID 25587268, 2014). "The results of the present study strongly suggest that TACE is involved in the pathogenesis of psoriasis through the release of TNF-α and EGFR ligands." (PMID 25384035, 2014). "Whereas little is known about the roles of the different DC subsets in psoriasis, recent reports indicate that DCs are an important source of IL-23, a cytokine that seems to have, along with TNF-α and IL-17, a central role in psoriasis pathology." (PMID 25216727, 2014). "It was demonstrated that mice lacking Jun-B/c-Jun in the epidermis showed a down-regulation of TIMP-3, resulting in the generation of a psoriasis-like phenotype through massive TNF-α shedding by TACE activation." (PMID 25384035, 2014). "Among the inflammatory molecules influencing the keratinocytes, TNF-α appears critical in sustaining most of the clinical manifestations of psoriasis, at both the joint and skin localizations." (PMID 25136144, 2014). "Anti-TNF-α therapies are now commonly used in a variety of inflammatory conditions including RA, psoriasis, psoriatic arthritis, AS, and Crohn's disease." (PMID 24600322, 2014). "Numerous studies have shown that serum levels of pro-inflammatory cytokines like tumor necrosis factor-α (TNF-α), interleukins, and interferon-γ were significantly higher in patients with psoriasis than in controls." (PMID 25541712, 2014). "Contradictory effects of anti-TNFα are also psoriasis-like cutaneous lesions and inflammatory bowel manifestations." (PMID 24991219, 2014). "Paradoxically, however, numerous studies have reported new-onset psoriasis and lichen planus, or worsening of existing psoriasis, following TNFα antagonist therapy in adult patients." (PMID 24802997, 2014). "Despite these clinical data pointing to an ambiguous function of TNFα in psoriasis and lichen planus, the role of TNFα, and in particular the contribution of each TNFR, in the regulation of skin inflammation has been scarcely studied." (PMID 24802997, 2014). "Psoriasis (Ps) is an autoimmune disease characterized by keratinocyte hyperproliferation and chronic inflammation, with increased expression of tumor necrosis factor (TNF) and vascular endothelial growth factor (VEGF)." (PMID 24587411, 2014). "Psoriasis is a T helper cell 1 response, leading to increased levels of TNF-α which are also found in the atherosclerotic plaque contributing to cardiovascular morbidity." (PMID 27433517, 2014). "Type II biomarkers have been identified for various psoriasis and atopic dermatitis therapies, including biomarkers representing Th17 pathway, monocyte activity (e.g. TNF-α), lymphocyte activity (Granzyme B) and type I interferon pathways." (PMID 25785188, 2014). "Paradoxically, numerous studies have reported new-onset psoriasis and lichen planus following TNFα antagonist therapy." (PMID 24802997, 2014). "The phenotype induced by IL-17 on RHE (as defined by the FCH between IL17 treated vs. control), was strongly enriched of genes in the psoriasis transcriptomes, and, to a lesser strength, with additive and synergistic TNF-α/IL-17 KC genes." (PMID 24587313, 2014). "The role for TNF-α in psoriasis has been well documented, and is supported by a number of studies showing successful therapeutic effects of its inhibitors." (PMID 25384035, 2014).